PGK1 (phosphoglycerate kinase 1)
Diseases named in the same sentence as PGK1 in open-access papers (continued):
Sharing a sentence is not in itself a finding about the gene and the disease.
tumor (continued). "This indicates that the high expression of PGK1 in bulk tumor tissues was positively correlated with the infiltration of Th2 and active dendritic cells in the tumor microenvironment." (PMID 36358653, 2022). "In addition, PGK1 could reverse the inhibition of tumor growth caused by NEAT1 knockdown." (PMID 35123484, 2022). "The TIDE database was used to analyze the effect of PGK1 expression in tumor tissues on the CTL number prediction ability of patient survival with immune therapy." (PMID 36358653, 2022). "PTEN directly interacts with PGK1 to control aerobic glycolysis in tumors, and PTEN encodes a protein with phosphatase activity that inhibits phosphorylated PGK1, which ultimately inhibits aerobic glycolysis and tumor cell proliferation." (PMID 35431949, 2022). "For example, tumor cells increase the expression of intracellular Pgk1 and glycolysis to facilitate energy production, but inhibit the secretion of Pgk1 in the hypoxic microenvironment." (PMID 35456967, 2022). "With regard to the underlying mechanism, it was reported that PIN1 is located in the nucleus and interacts with the glycolytic enzyme PGK1 to regulate tumor metabolism." (PMID 35983979, 2022). "PGK1 co-expressed genes were mostly involved in the hypoxia process, metabolism, immune microenvironment, and tumor microenvironment (TME)." (PMID 36358653, 2022). "Inhibition of PGK1 T243 phosphorylation can promote tumorigenesis and disrupt the therapeutic potential of the connection between macrophages and tumor cells." (PMID 37786890, 2022). "They found that PGK1 that had redistributed to the nucleus induced EMT, via repression of E-cadherin expression, through binding to the core promoter region of CDH1, while cytoplasmic PGK1 supported tumor cell proliferation through its metabolic function." (PMID 35326492, 2022). "The results indicated that PGK1 was more highly expressed in the tumor-infiltrating tissue type than normal and peripheral blood tissue types." (PMID 36358653, 2022). "PGK1 promotes tumor cell proliferation by inhibiting autophagy-mediated cell death through PRAS40 under normoxia, while shifting the binding partner from PRAS40 to Beclin1 to improve autophagy under hypoxia." (PMID 35058442, 2022). "Especially, the Venn map of the differential genes of tumor cells in different metastatic tumor cells vs. lung primary tumor cells indicated that PGK1 was a metastatic specific gene." (PMID 36358653, 2022). "When comparing the expression of PGK1 normal samples in the TCGA and GTEx (Genotype-Tissue Expression) databases with comparable tumor samples in the TCGA database, PGK1 was found to be considerably over-expressed in a variety of cancers, including LUAD." (PMID 36358653, 2022). "Phosphoglycerate kinase 1 (PGK1) has complicated and multiple functions in cancer occurrence, tumor progression and drug resistance." (PMID 35121728, 2022). "Meanwhile, we established a xenograft nude mouse model to observe PGK1-knockdown influence on tumor growth." (PMID 35121728, 2022). "The results suggested that the expression of PGK1 in tumor cells is significantly higher than that in normal epithelium." (PMID 36358653, 2022). "PGK1 exhibits pro-tumorigenic properties in vitro and in a xenograft tumor model by accelerating glycolysis and inducing CXCR4-mediated phosphorylation of AKT and ERK." (PMID 35121728, 2022). "As a protein kinase enzyme, PGK1 regulates autophagy initiation, mitochondrial function and tumor cell proliferation." (PMID 36077431, 2022). "The results indicated that both phosphorylated and total PGK1 protein were increased in tumor tissues and the expression level increased with the progress of tumor grade and stage." (PMID 36358653, 2022). "It has shown that PGK1-mediated tumor progression through regulating the glucose metabolism, as a vital enzyme to generate ATP in the glycolytic pathway." (PMID 35559258, 2022).
tumor (continued). "By analysing the gene expression data of KIRC tissues, we confirmed PGK1 is involved in the glycolysis process, which contributes to the tumor growth and sorafenib resistance in KIRC." (PMID 35121728, 2022). "CD24, CD74, PGK1 showed significantly higher expression in tumour tissue compared with tumour adjacent normal tissue, while STX11 and NFKBIA showed the opposite trend (p < .001 for all)." (PMID 34187256, 2021). "The expression of the tested HIF-1 target genes was apart from PGK1 significantly reduced in tumours from naphthofluorescein-injected mice compared to that in tumours from vehicle-injected mice, and HIF-1α mRNA levels were not affected in these tumours." (PMID 34621018, 2021). "The Spearman’s correlations between PGK1 expression level and tumor-infiltrating cells were analyzed using the TISIDB database." (PMID 34277429, 2021). "Abnormal expression level of PGK1 was detected not only in tumor tissues, but also in patients’ peripheral blood and saliva." (PMID 34291087, 2021). "In fact, NFAT5 facilitates cancer cell survival, boosting a glycolytic phenotype and tumor progression via transcription of PGK1." (PMID 33804240, 2021). "We further compared the mRNA expression of PGK1 in tumor samples and normal tissues using the UALCAN database." (PMID 34291087, 2021). "High expression of PGK1 is correlated with tumor proliferation, metastasis, occurrence, development and prognosis prediction." (PMID 35004842, 2021). "PGK1 is also a glycolytic enzyme that can be secreted by tumor cells to participate in angiogenesis." (PMID 34194463, 2021). "Quantitation of IHC staining also showed a higher staining percentage and intensity of PGK1/HTATSF1 in the tumor samples than in the normal group." (PMID 34091600, 2021). "According to the staining of paired tumor/normal tissues from clinical patients, we observed that a high expression of PGK1 commonly occurred in tumor tissues but was rare in normal adjacent tissues." (PMID 34091600, 2021). "Aside from the role of PGK1 as a glycolytic enzyme in different cell cycle intervals, PGK1 also shows an indispensible role in tumor metabolism." (PMID 34291087, 2021). "The results are consistent with previous studies and also indicate PGK1 acts energetically role in tumor cell metabolism." (PMID 34291087, 2021). "Through the TIMER2.0 web server, this study presented the differential expression of PGK1 in normal and tumor tissue specimens across pan-cancer." (PMID 34790279, 2021). "Phosphoglycerate kinase 1 (PGK1) is one of the key enzymes in the Warburg effect (also known as aerobic glycolysis), and involved in energy metabolism of tumor cells." (PMID 34852326, 2021). "We showed that the top-ranked target, PGK1, plays a key role in tumor cell glycolysis in PDAC and has high potential as a target for treating PDAC." (PMID 32241274, 2020). "The results showed that tumor growth was significantly slower in the PGK1 shRNA group and faster in the anti-miR-16-1-3p group than that in the control group." (PMID 33344462, 2020). "After analyzing lactate production and PGK1 expression of representative tumor tissues, we found that PGK1 expression was stimulated by anti-miR-16-1-3p, and anti-miR-16-1-3p promoted lactate production via PGK1." (PMID 33344462, 2020). "The results are keeping with the in vitro data and showed that glycosylation of PGK1 on T255 is critical for tumor growth in vivo." (PMID 31911580, 2020). "For examples, PKM2 has been reported to function as a kinase of multiple proteins including histone H3, STAT3 and SREBPs to promote tumor progression; and PGK1 phosphorylates Beclin1 and pyruvate dehydrogenase kinase isozyme 1 to support tumor development." (PMID 33277463, 2020). "What’s more, PGK1 can translocate to Mitochondria and function as a protein kinase to inhibit pyruvate dehydrogenase complex, and promote tumor progress by increasing glycolysis and suppressing mitochondrial tricarboxylic acid cycle." (PMID 32070368, 2020).
tumor (continued). "Analysis of the matched tumor samples from primary tumors and brain metastases also showed higher PGK1 expression levels in brain metastases than those in primary tumors." (PMID 32276500, 2020). "PGK1 is the first key enzyme to produce ATP in the glycolytic pathway, PGK1 is not only a metabolic enzyme but also a protein kinase, which mediates the tumor growth, migration and invasion through phosphorylation some important substrates." (PMID 33194424, 2020). "First, tumor cells secrete Pgk1 to promote early stages of metastasis through modulation of extracellular matrix (ECM) and cell signaling." (PMID 32338604, 2020). "Yajuan Zhang revealed that tumor-associated macrophages regulate the glycolysis of tumor cells by modulating the phosphorylation of phosphoglycerate kinase PGK1 in tumor cells, thereby promoting the development of pleomorphic glioblastoma." (PMID 32744303, 2020). "Loss of SMAD4 in PDAC is responsible for the high glycolytic capacity and tumor progression by upregulating PGK-1 expression, which has been shown to have dual roles in glycolytic catalysis and transcription factor activity in metastasis." (PMID 33256814, 2020). "PGK1 is demonstrated to be a tumor promoter, which can also affect the sensitivity and resistance of cancer cells to radiotherapy and chemotherapy." (PMID 32565733, 2020). "Neutralization of macrophage-derived IL-6 or inhibition of PGK1 T243 phosphorylation or PDPK1 in tumor cells markedly abrogates macrophage-promoted glycolysis, proliferation, and tumorigenesis." (PMID 33505964, 2020). "Among these glycolysis related genes, PGK1 has attracted our attention for its significant correlation with advanced tumor stage, and poor prognosis." (PMID 32070368, 2020). "Six pairs showed minimal PGK1 expression in either tumor or peritumoral tissues that prevented reliable quantitation." (PMID 31911580, 2020). "Among the remaining 44 pairs, 36 pairs showed relatively higher level of PGK1 in tumor tissues compared to the matching peritumoral tissues." (PMID 31911580, 2020). "PGK1 is secreted extracellularly by different types of tumors, acting as a disulfide reductase that serves to cleave plasminogen, thereby generating the tumor blood vessel inhibitor angiostatin." (PMID 33363463, 2020). "We performed pan-cancer analyses of PGK1 mRNA level and DNA methylation in 11,908 tumor tissues and 1582 paired normal tissues across 34 cancer types in The Cancer Genome Atlas datasets." (PMID 31578148, 2019). "Our previous studies revealed that in tumor cells, PGK1 possesses protein kinase activity in addition to performing its well-established glycolytic function." (PMID 31578148, 2019). "As an enzyme involved in generating valuable energy for the cell, especially in hypoxic conditions, PGK1 has been correlated with cancer development and progression in a variety of tumor types." (PMID 30679932, 2019). "During the glycolytic process, PGK1 contributes to ATP generation and participates in tumor progression." (PMID 31709724, 2019). "MiR-144 has been reported to target GSPT1 to inhibit the metastasis of CRC, and miR-548c-5p has been found to act as a tumor suppressor in CRC by targeting PGK1." (PMID 31803739, 2019). "Glycolytic enzymes such as PGK1 are involved in the initiation of autophagy in tumor cells under hypoxic conditions with deprivation of resources." (PMID 31683709, 2019). "MRI/PET-imaging of tumour growth and metastasis in in-vivo and subsequent ex-vivo models were concordant with immunohistochemical PGK1 staining." (PMID 31198853, 2019). "PGK1 expression was observed mostly in the cytoplasm of normal tissues and both in the cytoplasm and nucleus of tumor cells." (PMID 29416645, 2018). "As a glycolytic enzyme, PGK1 can provide energy to tumour cells and increase tumour migration, invasion and cell viability." (PMID 28903403, 2017). "It is possible that over-expressed PGK1 is one of the extrinsic factors of tumor cell radiosensibility." (PMID 28903403, 2017).
tumor (continued). "It looks like the interaction results in reduced secretion of PGK1, and enhancement of angiogenesis and tumor growth." (PMID 26131450, 2015). "Overall, both the modalities of 2D and 3D PCA plots supported the effectiveness of HIF-1α and PGK1 expression to define tumor sub-grouping based on differential expression of Notch genes." (PMID 25734817, 2015). "All 4 (18%) patients that died during the follow-up period showed PGK1-positive expression of the tumor, while of the 18 living patients only 3 showed positivity for PGK1." (PMID 24376734, 2013). "In another report, human α-fetoprotein (AFP) enhancer was combined with a housekeeping gene phosphoglycerate kinase-1 (PGK-1) promoter, to augment the activity of the weak tumor-selective AFP promoter." (PMID 21453283, 2011). "The secretion of PGK1 is regulated independently and inversely of its production and is consistent with the correlation between tumour hypoxia and angiogenesis." (PMID 19200351, 2009). "Phosphoglycerate kinase 1 (PGK1) plays an important role in tumour angiogenesis as a disulphide reductase." (PMID 19200351, 2009). "A second experiment was performed with 3 clones from another tumour; these expressed PGK-1 A, B and AB respectively." (PMID 6197985, 1984). "By modulating glycolytic flux and the production of metabolic intermediates, PGK1 could potentially affect tumor cell proliferation, survival, and invasion." (PMID 40771921, 2025). "While these genetic markers provide valuable information about the tumor’s genetic landscape, PGK1 expression levels may offer additional insights into the tumor’s metabolic state and functional behavior." (PMID 40771921, 2025). "In addition to glycolysis, PGK1 also contributes to nucleotide synthesis and redox balance, directly promoting tumor proliferation." (PMID 40464853, 2025). "Consequently, PGK1 is considered an important molecular marker of tumor occurrence and progression, and its role in tumor metabolic regulation provides a new perspective for cancer diagnosis and treatment." (PMID 40771921, 2025). "Consequently, TRIM8-mediated PGK1 K63 ubiquitination and ACAT1-dependent PGK1 acetylation are required for glycolysis, which promotes lactate accumulation and tumor angiogenesis." (PMID 41184227, 2025). "Additionally, PGK1 plays a role in various biological activities, including angiogenesis, autophagy, DNA replication and DNA damage repair, tumour growth, as well as cell proliferation and metastasis in many types of human tumour cells." (PMID 40055833, 2025). "In addition, GSE29044 had more differentially expressed GRPGs between normal and tumor tissues (CS, PGK1, HNRNPA1, ADPGK, YWHAZ, PTK2, and PGAM1) than GSE42568 (CS, HNRNPA1, ADPGK, and PTK2)." (PMID 40046063, 2025). "However, in CRC, our findings indicate that AAMP does not significantly activate Akt or EMT‐related signaling but instead promotes tumor cell proliferation primarily through PGK1 phosphorylation and glycolysis regulation." (PMID 40529105, 2025). "PGK1 is upregulated in cancers and promotes glycolysis in tumor cells." (PMID 41426311, 2025). "Recently, the role of PGK1 in tumor biology has received increasing attention." (PMID 40771921, 2025). "Further analysis of PGK1 expression across clinicopathological characteristics revealed that patients with poorly differentiated tumors, TNM stages III–IV, lymph node metastasis, and tumor diameter ≥1.0 cm exhibited higher PGK1 expression levels in cancerous tissues." (PMID 40771921, 2025). "We speculate that PGK1 may enhance the activation of this pathway, thereby promoting tumor progression." (PMID 40771921, 2025). "In addition, polarized M2 macrophages enhance phosphoglycerate kinase 1 (PGK1) threonine (T) 243 phosphorylation in tumor cells by secreting IL-6." (PMID 40131539, 2025). "One plausible mechanism is that PGK1 may influence tumor biological behavior by regulating metabolic pathways." (PMID 40771921, 2025).
tumor (continued). "Phosphoglycerate kinase 1 (PGK1) is a key enzyme involved in tumor lactate metabolism." (PMID 40016971, 2025). "Previous studies suggest that AAMP may regulate phosphorylated PGK1 through direct interaction, further influencing tumor cell proliferation and metabolic characteristics." (PMID 40529105, 2025). "For example, acetylation of PGK1 initiates hypoxia-induced autophagy and sustains tumor growth." (PMID 38163864, 2024). "PTEN inhibits the autophosphorylation of PGK1, thereby directly inhibiting tumor glycolysis." (PMID 38933335, 2024). "In addition, IL-6 secreted by polarized TAMs enhances the phosphorylation of PGK1 in tumor cells and activates PGK1, demonstrating a novel mechanism by which macrophages promote tumor growth by regulating glucose metabolism." (PMID 39594816, 2024). "To assess the clinical significance of FTSJ1 in glucose metabolism in NSCLC, we investigated the relationship between SUVmax value (a surrogate indicant for aerobic glycolysis) of PET-CT scan and the expression levels of FTSJ1 and PGK1 proteins in tumor tissues resected from 19 NSCLC patients." (PMID 39695074, 2024). "In addition, TRIM50 suppressed glycolysis and tumor progression by mediating ubiquitination and degradation of Phosphoglycerate Kinase 1 (PGK1), a key enzyme in the glycolytic pathway." (PMID 39768197, 2024). "Additionally, tumorigenicity experiments displayed that PGK1 knockdown suppressed tumor formation in nude mice." (PMID 38163864, 2024). "The abnormal expression of PGK1 can affect the migration and invasion of tumor cells as well." (PMID 38247832, 2024). "PGK1 not only functions as a metabolic enzyme but also as a protein kinase that regulates signal transduction pathways closely related to cell growth, division, and tumor development." (PMID 39594816, 2024). "To verify whether circGLIS3 plays the role of tumor promoter via PGK1 by sponging miR-1343-3p, we carried out a rescue experiment." (PMID 38459513, 2024). "As anticipated, a noteworthy suppression of tumor growth was observed upon the depletion of PGK1." (PMID 38163864, 2024). "PGK1 serves as a core gene in tumour metabolism, particularly glycolysis, and plays a determining role in evaluating immune therapy response, as indicated by the over‐expression of PGK1 in immunosuppressive cells and significant correlations to the expression of ICMs." (PMID 38693853, 2024). "However, high expression of PGK1 in the extracellular matrix can inhibit tumour angiogenesis through the production of angiostatin, which plays a role in inhibiting tumour proliferation." (PMID 38288377, 2024). "PGK1 is highly expressed in various tumours (liver cancer, renal clear cell carcinoma, lung adenocarcinoma), and its high expression within tumour cells promotes tumour cell proliferation and metastasis." (PMID 38288377, 2024). "Whether the occurrence and development of tumours are related to the K220 acetylation of PGK1 needs to be further studied." (PMID 37723547, 2023). "Therefore, extracellular PGK1 plays an inhibitory role in tumour growth and metastasis under certain conditions, and it is essential for PGK1 to be properly balanced to promote cancer." (PMID 37723547, 2023). "SEMA5A, but not the truncated protein rSEMA5A-ΔTSP, could induce PKM2 or PGK1 expressions in tumor cells residing in metastatic niches, elucidating the importance of SEMA5A-PLXNB3 axis in the Warburg effect triggering." (PMID 36741230, 2023). "For example, PGK1 could regulate the β-catenin expression and participate in the regulation of tumor metastasis." (PMID 36807568, 2023). "In brief, the impact of PGK1 on tumour development largely depends on cellular metabolism." (PMID 37723547, 2023). "Furthermore, we first demonstrated that high expression of circHMCU enhanced BC cell malignant phenotypes in vitro and tumor growth in vivo by regulating miR-4458/PGK1 axis." (PMID 36949536, 2023).